SETD2 (SET domain containing 2, histone lysine methyltransferase)
Diseases named in the same sentence as SETD2 in open-access papers (continued):
Sharing a sentence is not in itself a finding about the gene and the disease.
lung adenocarcinoma (continued). "Intriguingly, it has been seen that driver fusions in lung adenocarcinomas co-occur with SETD2 mutations (16% of cases) in contrast with lung adenocarcinomas with EGFR, KRAS, BRAF and MET mutations, where the frequency of SETD2 mutations is only 2%." (PMID 32516941, 2020). "Patients in Cluster 1 exhibited a normal-like genomic pattern with the lowest level of genomic alterations; however, SETD2 (one established mutation driver gene of lung adenocarcinoma) mutated only in these patients (P = 1.94×10-3)." (PMID 33042282, 2020). "SETD2 mutations partly explain the resistance to PD-1 and PD-L1 antibodies in lung adenocarcinomas driven by fusions, making the screening for SETD2 mutations advisable." (PMID 32516941, 2020). "SETD2 is among the most mutated chromatin factors in kidney renal clear cell and lung adeno carcinomas." (PMID 25484917, 2014). "Deregulation of histone methyltransferases was reported for oncogenic transformation of human bronchioepithelial cells and mutations of the histone methyltransferase, SETD2, were recently identified by large scale DNA sequencing of lung adenocarcinomas." (PMID 24216980, 2013). "Therefore, it will be of interest in future work to understand the relationship between SETD2 loss and other somatic mutations involved in lung adenocarcinoma development." (PMID 40961184, 2025). "The inclusion of lymphovascular invasion, spread through air spaces, or other pathologic variables may also elucidate the tumor biology of SETD2-mutated lung adenocarcinoma." (PMID 41228333, 2025). "SETD2-mutated lung adenocarcinoma had a higher unadjusted one-, three-, and five-year RFS." (PMID 41228333, 2025). "Of these, 67 SETD2-mutated lung adenocarcinomas met inclusion criteria." (PMID 41228333, 2025). "Moreover, SETD2 inactivation enhanced mTORC1-associated gene expression in a KRAS-driven lung adenocarcinoma model in vivo, whereas mTORC1 inhibition enhanced therapeutic susceptibilities in SETD2-inactivated cancer." (PMID 38036730, 2023). "Furthermore, loss of heterozygosity (LOH) at chromosome 3p, where SETD2 resides, is commonly detected in lung adenocarcinoma." (PMID 36810256, 2023). "To determine whether SETD2 deficiency is associated with increased mTORC1 activity, we first evaluated human lung adenocarcinomas using reverse phase protein array (RPPA) data from the Cancer Proteome Atlas30,31." (PMID 36899051, 2023). "Therefore, our study nominates OXPHOS and mTORC1 inhibition as a targeted therapy for SETD2-deficient lung adenocarcinoma." (PMID 36899051, 2023). "SETD2 is one of the most frequently mutated chromatin-modifying genes across different cancer types, with the highest mutation rate in clear cell renal cell carcinoma (ccRCC, 13%) followed by lung adenocarcinoma (9%)." (PMID 36810256, 2023). "We identified samples from the TCGA kidney renal papillary cell carcinoma (KIRP) and lung adenocarcinoma (LuCa) data collections that harbored SETD2 mutations (two tumor types with appreciable numbers of SETD2 mutant tumors in TCGA datasets) and analyzed them alongside the KIRC dataset." (PMID 26646321, 2016). "Finally, given the dearth of investigations into SETD2-mutated lung adenocarcinoma, we hope this manuscript is hypothesis-generating and lays the foundation for future research." (PMID 41228333, 2025). "As such, we sought to interrogate the consequences of Setd2 inactivation in KRAS-driven lung adenocarcinoma in order to better understand how SETD2 deficiency drives early and widespread tumor growth and identify intrinsic therapeutic vulnerabilities that may exist." (PMID 36899051, 2023).
lung adenocarcinoma (continued). "In lung adenocarcinoma, SETD2 inactivation has been validated to accelerate KRAS-driven tumor growth in murine models." (PMID 41228333, 2025). "The expression levels of SETD2 in most tumors vs. normal tissues were downregulated, and SETD2 inhibits the growth of these tumor, for example, in lung adenocarcinoma 7 and in kidney cancer." (PMID 39668826, 2024). "This means that a decrease in SETD2 expression in lung adenocarcinoma tumors leads to an increase in CXCL1 expression." (PMID 38673949, 2024). "SETD2 inactivation leads to heightened mTORC1 signaling, oxidative metabolism and protein synthesis in KRAS-driven mouse models of lung adenocarcinoma, contributing to the understanding of how SETD2 deficiency drives early and widespread tumor growth." (PMID 36899051, 2023). "SETD2, a H3K36 trimethyltransferase, is the most frequently mutated epigenetic modifier in lung adenocarcinoma, with a mutation frequency of approximately 9%." (PMID 36810256, 2023). "Of note, similar results were observed in TCGA‐LUAD (lung adenocarcinoma) and TCGA‐COAD (colorectal adenocarcinoma) datasets as well, further indicating the role of SETD2 deficiency in reshaping the immune TME, especially for neutrophils." (PMID 36453584, 2023). "Here we identify heightened mTORC1-associated gene expression programs and functionally higher levels of oxidative metabolism and protein synthesis as prominent consequences of Setd2 inactivation in KRAS-driven mouse models of lung adenocarcinoma." (PMID 36899051, 2023). "In this report, we present for the first time an unreported case of lung adenocarcinoma with double ALK fusions of echinoderm microtubule-associated protein like 4 (EML4) and histone methyltransferase (SETD2), which is sensitive to alectinib." (PMID 37055606, 2023). "Among candidate co-operating events to be examined is the inactivation of SETD2, a histone methyltransferase recently reported to be mutated in EML4-ALK fusion-driven lung adenocarcinoma." (PMID 33761896, 2021). "SETD2 mutant primary ccRCCs, papillary renal cell carcinomas, and lung adenocarcinomas all demonstrated a DNA hypermethylation phenotype that segregated tumors by SETD2 genotype and advanced grade." (PMID 26646321, 2016). "Although our study identifies a potentially more favorable cancer phenotype, further translational investigation is needed to conclusively state that SETD2-mutated lung adenocarcinoma has more favorable biology than non-mutated cancers." (PMID 41228333, 2025). "Together, these data support that SETD2 is a tumor-suppressor gene in lung adenocarcinoma." (PMID 36810256, 2023). "Furthermore, copy number analysis also detected the loss of chromosome 9 in these tumors, which the Keap1 and Setd2 genes, both of which have been shown to function as tumor suppressors in KrasG12D-driven mouse model of lung adenocarcinoma." (PMID 35482806, 2022). "Moreover, low SETD2 expression is correlated with reduced overall survival of lung adenocarcinoma (LUAD) patients." (PMID 34715919, 2021). "To begin to assess whether the impact of SETD2 mutations on 5mC localization was conserved in other tumor types, we expanded our analysis to two large public datasets, papillary RCC and lung adenocarcinoma." (PMID 26646321, 2016). "Moreover, SETD2 has also been involved in a cisplatin-resistance mechanism in lung adenocarcinoma." (PMID 39591760, 2025).
lung adenocarcinoma (continued). "Notably, SETD2 mutations often cooccur with other well-established driver mutations, such as KRAS, EGFR, and BRAF, that activate the RTK/RAS/RAF pathway in lung adenocarcinoma, suggesting that SETD2 inactivation probably cooperates with these driver mutations to promote lung tumorigenesis." (PMID 36810256, 2023). "The parallels between the consequences of SETD2 and LKB1 inactivation are all the more provocative given an apparent functional-genetic epistatic relationship in KRAS-driven mouse models and their mutually exclusive pattern of mutation in human of lung adenocarcinoma patients." (PMID 36899051, 2023). "Here, we show that SETD2 functions as a potent tumor suppressor in a KRASG12C-driven lung adenocarcinoma (LUAD) mouse model, and that acetylation enhances SETD2 in vitro methylation of H3K36 on nucleosome substrates." (PMID 40462961, 2025). "In lung adenocarcinoma, there is decreased expression of histone H3 lysine 36 methyltransferase SET-domain-containing 2 (SETD2)." (PMID 38673949, 2024). "Our work uncovers a role for SETD2 in constraining mitochondrial OXPHOS and mTORC1 signaling to limit cellular proliferation in the context of KRAS-driven lung adenocarcinoma." (PMID 36899051, 2023). "In another study, the methyltransferase SETD2 was found to inhibit tumor growth and metastasis through STAT1-IL-8 signaling-mediated epithelial-mesenchymal transition in lung adenocarcinoma." (PMID 36726839, 2023). "The tumor suppressive function of the chromatin modifier SETD2, at least in the context of KRAS-driven lung adenocarcinoma, is therefore to limit pro-proliferative metabolic pathways by restricting oxidative metabolism and protein synthesis." (PMID 36899051, 2023). "We identified alterations in genes involved in chromatin remodeling (PBRM1, SETD2), oxidative stress (CUL3, SOD2), immune response (CSMD3, SYK), and gamma-aminobutyric acid receptor signaling (GABRD, GABRG1) in lung adenocarcinoma." (PMID 24576404, 2014). "To confirm that the effects of SETD2 depletion were not just confined to ccRCC, we examined the effects of SETD2 depletion A549 lung adenocarcinoma cells." (PMID 40961184, 2025). "There was no significant age difference in the SETD2 cases and SETD2 control groups across all cancers, except lung adenocarcinoma." (PMID 37528416, 2023). "Second, SETD2 inhibits CXCL1 gene expression via catalyzing H3K36me3 formation within the promoter of CXCL1 and then indirectly influences related downstream signaling pathways to attenuate the proliferation of lung adenocarcinoma cells and the growth of tumors." (PMID 34715919, 2021). "However, the role of SETD2 in lung adenocarcinoma (LUAD) has not been well documented." (PMID 33223508, 2020).
leukemia (35 papers, 2014 to 2026). A malignant (clonal) hematologic disorder, involving hematopoietic stem cells and characterized by the presence of primitive or atypical myeloid or lymphoid cells in the bone marrow and the blood. "SETD2 mutations are highly prevalent in MLL-r leukemia, and for this study, we utilized an MLL-fusion background." (PMID 40300107, 2025). "SETD2 mutations have been reported in 6 % of acute leukemia with 22 % enriched in MLL (Mixed Lineage Leukemia)-rearranged leukemia." (PMID 39591760, 2025). "Since transcriptomic data from leukemia patients with SETD2 mutations are unavailable in public databases, we established the signature of Setd2-deficient leukemia using gene expression data from leukemic cells derived from previously generated mouse models." (PMID 40300107, 2025). "Using the L1000 database, we identified drugs with varying potency to reverse the gene expression signatures of Setd2-deficient leukemia." (PMID 40300107, 2025). "Although PRMT5-i have shown promise in treating MLL-r leukemia, our results suggest that additional mutations, such as those in SETD2, should be considered for their potential impact on PRMT5-i efficacy." (PMID 40300107, 2025). "Given the promising pre-clinical results of PRMT5-i in leukemia, our findings suggest that SETD2 mutation status should be considered in treatment strategies." (PMID 40300107, 2025). "Four drug classes overlapped between both sets of Setd2-deficient leukemia signatures, including ATM/ATR-i, BET-i, BTK-i, and G9a-i." (PMID 40300107, 2025). "Subsequently, we compared the Setd2-deficient leukemia signature with drug-response transcriptional profiles from the L1000 database to predict potential therapeutic agents, using a method adapted from previous studies." (PMID 40300107, 2025). "Loss of SETD2 is associated with chemoresistance in MLLr leukemia, acute lymphocytic leukemia (ALL), and chronic myelogenous leukemia (CML)." (PMID 38036730, 2023). "Of note, mutations in SETD2 have been reported to confer resistance to DNA-damaging chemotherapy in leukemia." (PMID 36810256, 2023). "Studies have shown that SETD2 plays a tumor suppressor role in chronic myeloid leukemia (CML), and SETD2 loss significantly promotes imatinib resistance and leukemia stem cell enrichment in CML cells." (PMID 37359376, 2023). "In line with that, the heterozygous loss of SETD2 caused resistance to DNA-damaging agents in cell lines and mouse models of leukemia." (PMID 34576219, 2021). "Pathogenic SETD2 mutations have been detected in several cancers, including renal cell carcinomas, breast carcinomas, lung cancers, central nervous system tumors, leukemia, and lymphoma in particular MEITL and hepatosplenic T-cell lymphoma." (PMID 33260897, 2020). "A recent study confirms that loss-of-function SETD2 mutations facilitate the initiation of leukemia and impair DNA damage recognition, leading to resistance to therapy." (PMID 32849799, 2020). "Several reports have characterized the role of normal and mutated SETD2 in leukemia with MLL (Mixed Lineage Leukemia)-fusion genes." (PMID 30818762, 2019). "In line, heterozygous SETD2 loss caused chemotherapy resistance in leukemia cell lines and mouse models." (PMID 30818762, 2019). "Alterations in the SETD2 gene are also present in leukemia patients, where they are associated with aggressive disease and relapse." (PMID 30818762, 2019). "This was recently confirmed, as heterozygous loss of SETD2 in leukemia resulted in resistance to DNA-damaging agents." (PMID 30818762, 2019). "The contribution of cells carrying sgRNA-induced mutations in the Setd2 SET domain to leukemia development was investigated by flow cytometric analysis of mCherry expression upon transplantation." (PMID 29777171, 2018). "In consequence, SETD2 loss led to hyper-sensitization of MLL-leukemia cells to small-molecule-mediated DOT1L inhibition, which provides a rationale for potential future combination therapies in AML." (PMID 29777171, 2018).
leukemia (continued). "While cells expressing a control sgRNA showed robust contribution to MLL-ENL-induced leukemia in vivo (56%), cells carrying Setd2-mutations induced by two different sgRNAs were clearly underrepresented in the leukemic population (5–25%)." (PMID 29777171, 2018). "This is in line with a recent study showing that SETD2 mutations in leukemia impair the DNA damage response, thereby leading to chemotherapy resistance." (PMID 29777171, 2018). "This indicates that loss of functional SETD2 facilitates initiation as well as progression of leukemias." (PMID 27191891, 2016). "Indeed, heterozygous SETD2 loss in leukemia cells expressing a MLL (Mixed Lineage Leukemia)-AF9 fusion protein was found to accelerates leukemogenesis driven by the MLL fused gene." (PMID 39591760, 2025). "Inactivating SETD2 mutation was described as a mechanism of chemoresistance in leukemia." (PMID 40282457, 2025). "A similar effect on DNA damage checkpoint was also observed in the mammalian system, in which a leukemia-associated SETD2 F2478L point mutation caused a decrease in the activating phosphorylation of checkpoint kinases CHK1 and CHK2 and cyclin-dependent kinase (CDK)-inhibiting WEE1 kinase." (PMID 35581654, 2022). "SETD2 alterations, as well as autophagy deficiencies, have been associated with several pathophysiologies, including neurodevelopmental disorders, Luscan-Lumish syndrome and several cancer types such as renal cell carcinoma, breast cancer or leukemia." (PMID 36371383, 2022). "In leukemias, SETD2 usually undergoes loss of function mutations and deletions." (PMID 32859239, 2020). "Therefore, checkpoint defects caused by SETD2 inactive mutation accelerate the development of leukemia and lead to resistance to standard cytarabine-based chemotherapy." (PMID 32859239, 2020). "Deregulation of these processes caused by loss or mutation of SETD2 might result in abnormal transcription that is associated with leukemia development." (PMID 30818762, 2019). "First, a mutator phenotype induced by SETD2 inactivation could increase the mutational diversity and thus, adaptability of the leukemia, leading to clonal survival." (PMID 30922329, 2019). "In contrast complete loss of SETD2 strongly impedes leukemia development." (PMID 29777171, 2018). "SETD2 mutations appeared to be most frequent in leukemias that carried a MLL gene rearrangement." (PMID 27191891, 2016). "Setd2 is also a tumor suppressor mutated frequently in leukemia." (PMID 25848745, 2015). "Indeed, the downregulation of H3K36me3 by SETD2 mutation can attenuate leukemia cell proliferation." (PMID 35581654, 2022). "Here, we present the enzymatic and structural characterization of the SETD2 L1609P mutant enzyme identified in leukemia." (PMID 41654133, 2026). "In SETD2 LOF mutations, these processes are often dysregulated, resulting in aberrant gene expression and contributing to the aggressiveness of SETD2-mutant leukemia." (PMID 40300107, 2025). "Given the established role of let-7a in MYC suppression, these findings suggest a potential mechanism by which G9a inhibitors induce MYC downregulation in SETD2-mutant leukemia." (PMID 40300107, 2025). "For instance, in leukemia where alteration of SETD2 induces a resistance to chemotherapy, treatment with JIB-04, an inhibitor of the H3K9/36me3 demethylase KDM4A, restored H3K36me3 levels and chemotherapy sensitivity in vitro and in vivo." (PMID 39591760, 2025). "To explore potential therapeutics for SETD2-mutant leukemia, we employed an integrated approach combining computational prediction with epigenetic compound library screening." (PMID 40300107, 2025). "SETD2 is also a tumor suppressor, with SETD2 mutations being found in a wide range of cancers, including in acute leukemia where KMT2A-rearranged leukemias more frequently harbor SETD2 mutations than non-KMT2A-rearranged leukemias." (PMID 41279818, 2025).